CAT (catalase)
Diseases named in the same sentence as CAT in open-access papers (continued):
Sharing a sentence is not in itself a finding about the gene and the disease.
Arthritis (24 papers, 2007 to 2025). Inflammation of a joint. "Positive correlations between IFN I-score, its components, and disease activity, CAT activity, cheilitis, and arthritis were observed." (PMID 38420360, 2024). "Cocoa-enriched diets modify the SOD and CAT activities in the macrophages of heat-killed Mycobacterium butyricum suspension-induced arthritis in rat." (PMID 35892652, 2022). "In the liver of the AA model, an impaired ROS-scavenging system in arthritis was established by analyzing oxidative injury parameters, the levels and production of ROS, and antioxidative activities (diminished CAT activity)." (PMID 36296709, 2022). "From our study, induction of arthritis resulted in reduced expression of catalase and superoxide dismutase as well as the reduction in levels of reduced glutathione." (PMID 36061079, 2022). "There was however an increase in catalase, superoxide dismutase expression, and increased reduced glutathione levels in arthritis rats after PSRE administration." (PMID 36061079, 2022). "In this regard, an superoxide dismutase (SOD) 2/catalase mimetic (EUK-134) that supposedly targets the mitochondria has shown promising effects in the attempt to prevent muscle weakness in rats with arthritis and in a rodent model of pulmonary hypertension." (PMID 33146370, 2020). "Conversely, the diminished catalase and superoxide dismutase activities and glutathione (GSH) levels caused by arthritis were totally or partially prevented." (PMID 31618993, 2019). "Our findings show that CAT activity was significantly decreased in the cerebral cortex, spinal cord, and paw tissues of arthritis mice, consistent with previous studies reporting increased mitochondrial TBARS production and reduced CAT activity in these regions during inflammation." (PMID 41011247, 2025). "The injection of Freund’s complete adjuvant (FCA) as an arthritis inducer resulted in a significant increase in oxidative stress markers, as evidenced by a reduction in catalase (CAT) activity and an elevation in malondialdehye (MDA)—an indicator of lipid peroxidation—in the arthritic control group." (PMID 40305360, 2025). "The rams suffering from arthritis exhibited abnormally low levels of gene expression for SOD3, CAT, GPX and ATOX1." (PMID 40005882, 2025). "In arthritis‐induced oxidative stress model in rats the supplementation of J. regia L. or its extract resulted in increased levels of SOD, CAT, and renal and hepatic tissues structural integrity." (PMID 41179368, 2025). "The SOD3, CAT, GPX and ATOX1 genes were expressed at substantially lower levels in arthritis-affected rams." (PMID 40005882, 2025). "The expression of the SOD3, CAT, GPX and ATOX1 genes was significantly reduced in the rams with arthritis." (PMID 40005882, 2025). "To confirm the role of oxidative stress in CFA-induced arthritis and related conditions, we measured TBARS levels and CAT activity in the cerebral cortex, spinal cord, and paws of mice." (PMID 41011247, 2025). "In arthritis-induced rats complemented with fustin, the prominence of antioxidant enzymes such as GSH, CAT, and SOD was overexpressed, and the eminence of lipid peroxidation was decreased, confirming the antioxidant activity." (PMID 37520245, 2023). "Induction of arthritis even aberrantly impairs the anti-oxidant defense system by almost depleting as evident here the vital line of defenses (GSH, SOD and CAT) against toxic free radicals." (PMID 30567538, 2018). "Interestingly, antioxidant treatment with a SOD/catalase mimetic resulted in a reduced amount of 3-NT and MDA adducts on actin, less actin aggregate formation and counteracted arthritis-induced muscle weakness." (PMID 33146370, 2020). "In their study combined scavenging with ECSOD and catalase did not have an additive protective effect on arthritis though each antioxidant gene had a protective effect as in our study, in which each also suppressed demyelination and disruption of the blood-brain barrier." (PMID 17242675, 2007).
Arthritis (continued). "This research described the antioxidant (SOD3, CAT, GPX, ATOX1 and COX18) and immunological (IL-1α, IL-1β, IL-6, IL-10, TNFα, NCF4, NFKB, TMED, FCAMR and iNOS) genes in rams that had arthritis and those that did not." (PMID 40005882, 2025). "Treatment of AIA rats with EUK-134 (3 mg/kg/day), a superoxide dismutase/catalase mimetic, prevented both the decrease in tetanic force and the formation of actin aggregates in EDL muscles without having any beneficial effect on the arthritis development." (PMID 26161253, 2015).
heart failure (24 papers, 2012 to 2025). Inability of the heart to pump blood at an adequate rate to meet tissue metabolic requirements. "The causal role of oxidative stress in heart failure is also supported by gene transfer studies of the three primary antioxidant enzymes (SODs, catalase, and glutathione peroxidase), of thioredoxin, and of heme oxygenase-1." (PMID 34829874, 2021). "Similarly, overexpression of mitochondrial‐targeted catalase reduces markers of heart failure (Anp and Bnp) in DNA repair‐ deficient mice." (PMID 36734200, 2023). "Finally, to determine whether increased ROS contributes to cardiac failure in Ckmm‐Cre+/−;Ercc1−/fl mice, we generated DNA repair‐deficient mice expressing mitochondrial‐targeted human catalase (mitCAT)." (PMID 36734200, 2023). "Catalase overexpression in the heart prevents progression into heart failure and influences myocardial remodeling by reducing fibrosis." (PMID 37760023, 2023). "As previously reported, overexpression of mitochondrial catalase attenuates pressure overload-induced heart failure." (PMID 37780627, 2023). "For instance, a four week exercise-based cardiac rehabilitation programme resulted not only in improvement of functional and hemodynamic parameters but also increased the activity of circulating catalase and superoxide dismutase in heart failure patients." (PMID 35053101, 2022). "It has been shown that overexpression of mitochondrial catalase attenuates pressure overload-induced heart failure, demonstrating that scavenging mitochondrial ROS preserves the fatty acid oxidation pathway in heart failure." (PMID 29421236, 2018). "It has been reported that increased oxidative stress in human end-stage heart failure results in a specific upregulation of CAT gene expression." (PMID 22569420, 2012). "The effect of ethanolic peel extract on the concentration of oxidative stress markers (CAT, SOD, MnSOD, GR, GST, GPx, TOS, SH, and MDA), biomarkers of heart failure (cTnI, GAL-3), and alternations in tissue architecture was assessed." (PMID 37371882, 2023). "It is known that increased ROS production during heart failure is accompanied by reduced antioxidant mechanisms, i.e., decreased activities of SOD, CAT, and GPx, as well as the activation of the pro-inflammatory NF-κB." (PMID 36294901, 2022). "In this study, RES markedly reduced activities of CAT, SOD, and GSH induced by HFpEF, which further verified an anti-oxidative role of RES not only in heart failure with reduced ejection fraction (HFrEF) but also in the setting of HFpEF." (PMID 34177571, 2021). "In this study, we reported that ASI is effective in maintaining the levels of CAT, GSH and SOD and preventing the leakage of CK, which suggested that ASI protected against heart failure partly by alleviating oxidative stress." (PMID 33253607, 2020). "In the present study, TPT treatment can significantly decrease myocardium MDA level and increase GSH level, SOD, CAT and GSH-Px activities in heart failure rats." (PMID 22569420, 2012). "Superoxide dismutase enzymes, catalase, glutathione peroxidase, gap junction protein alpha, myosin heavy chains, and zinc finger transcription factor GATA4 were located upstream of several genes in heart failure network." (PMID 35311161, 2022). "In the future, these results may provide the key treatment for human heart failure; they confirm the efficacy of the combined effect of SOD and CAT activity in blocking oxidative stress." (PMID 36246071, 2022). "In addition, targeted superoxide anion inhibition could improve post-MI heart failure because post-MI heart failure is accompanied by a significant increase in free radical-mediated lipid peroxidation and plasma superoxide anion levels, but decreased catalase, glutathione, and SOD plasma levels." (PMID 35681549, 2022). "Moreover, scavenging ROS by overexpressing catalase (CAT) ameliorates LV cardiac hypertrophy, fibrosis, and diastolic dysfunction, and attenuates the phenotype of heart failure." (PMID 33802566, 2021).
injury (24 papers, 2011 to 2025). Damage inflicted on the body as the direct or indirect result of an external force, with or without disruption of structural continuity. "GTE reduces GSH, SOD and CAT levels in the lungs of a cigarette smoke-induced lung injury rat model." (PMID 38745671, 2024). "Our experiments showed that the activities of SOD, GSH, and CAT in STZ-induced nerve injury mice were significantly lower than those in the control group, and the activity of MDA was increased, which is consistent with previous reports." (PMID 38790466, 2024). "In particular, vanillin, a kind of bioactive compound in KRPBE, significantly increased GSH, SOD, CAT and GPx levels in rats with carbon tetrachloride-induced acute brain injury, as well as decreasing MDA levels, resulting in significant brain protection." (PMID 36039041, 2022). "Our results encourage the further study of catalase-loaded nanoparticles as a pharmaceutical intervention in perinatal brain injury." (PMID 34452092, 2021). "Some studies aiming at identifying HSYA in the brain tissues of rats suggested that HSYA, which increased the activities of superoxide dismutase and catalase, can be potentially used as a neuroprotective agent for traumatic brain injury." (PMID 31198790, 2019). "Retinal transfection of AAV-expressing CAT and superoxide dismutases 2 (SOD2) prolonged cone photoreceptor survival in mice during retinal degeneration, and AAV-CAT also exerts neuroprotective effects on retinal ganglion cells in ischemia-induced retinal injury in rats." (PMID 36187472, 2022). "In addition to its potential in increasing SOD, GPx, and catalase production, it is able to induce the HO-1 protein expression in order to defence against oxidative damage in LPS-induced lung injuries." (PMID 28368327, 2017). "However, the present study found that the widely used CAT inhibitor ATZ significantly protected mice from APAP-induced acute liver injury." (PMID 25884831, 2015). "Interestingly, it has been demonstrated in animal models, that an increase of catalase activity significantly suppresses the subsequent I/R-induced acute liver injury." (PMID 23226251, 2012). "ROS removal is regulated by many antioxidant enzymes, including SOD1, SOD2, GPX, and catalase, and overexpression of SOD2 protects against alcohol-induced liver injury." (PMID 24069053, 2013). "Moreover, compared to the normal control group, alcohol-induced brain injury rats exhibited significantly reduced activities of SOD, CAT, and GSH-PX in brain hippocampal tissue (P<0.0001, P<0.0001, and P<0.0001)." (PMID 39229571, 2024). "Decreased SOD, GSH-PX, CAT, and GSH levels have been observed in patients with alcoholic liver injury, indicating that decreased antioxidant defense mechanisms contribute to the development of liver injury." (PMID 37432394, 2023). "In addition, CS treatment increased the activity of antioxidant enzymes, including catalase and SOD, in animal models of spinal cord injury, bleomycin-induced lung injury and chronic stress-related brain damage." (PMID 36552549, 2022). "Previous studies have shown that lotus leaf extract enhances the antioxidant capacity in alcohol-induced gastric injury mice and high-fat diet-induced obese mice, including the ability to increase SOD, CAT, GSH, and GSH-PX and decrease the levels of MDA and NO." (PMID 34992717, 2021).
memory impairment (24 papers, 2012 to 2025). "Studies have confirmed the abnormal alterations in MDA, SOD, and CAT activities associated with memory impairment after sleep deprivation." (PMID 35126189, 2021). "It has been demonstrated that scopolamine associated increase in oxidative stress direct increased lipid peroxidation and reduced SOD, CAT, and GPx in rat brain, which causes memory impairment and neuronal cell death." (PMID 29875670, 2018). "Furthermore, treatment with VPA decreased SOD, GPx, and catalase activities, demonstrating that it causes intracellular oxidative stress and abatement of antioxidant enzymes, both of which are correlated with memory impairment." (PMID 34804374, 2021). "↑ GSH, SOD, CAT, motor performance, histopathological changes, and neurological scores. ┴ Memory impairment, MDA and NO formation." (PMID 40656619, 2025). "SOD and CAT activities and NO contents in the brain tissue of mice with learning and memory impairment were detected after the behavioral experiments." (PMID 35924065, 2022). "The supplementation of walnut suspension to rats with scopolamine‐induced memory impairment ameliorated memory function through increasing SOD, CAT, GSH‐Px, and lowering MDA levels in brain tissue." (PMID 41179368, 2025). "In a model of D-galactose-induced memory impairment in rats, THP reduced oxidative parameters (MDA and NO) and enhanced antioxidant parameters (SOD, CAT, and GSH)." (PMID 34760017, 2021). "Black ginseng extract significantly reversed scopolamine (SCOP)-induced memory impairment in amnesic mice and also reduced escape latency by decreasing malondialdehyde (MDA) levels and restored superoxide dismutase (SOD) and catalase (CAT) activities." (PMID 31091790, 2019). "In the case of oxidative stress the levels of CAT, SOD and GSH are reduced which can lead to death of neurons leading to memory impairment." (PMID 31121979, 2019). "Amongst natural entities, oral administration of polydatin could dramatically reduce the production of malondialdehyde (MDA) and increase the activity of the antioxidants SOD and catalase (CAT) to protect learning and memory impairments in vivo." (PMID 34641529, 2021). "It was observed that the hypoxia-induced memory impairment in mice is related with enhanced expression of Hif-1α, which could have affected the levels of the antioxidative stress enzymes such as SOD and CAT." (PMID 26413121, 2015). "It significantly modulated the oxidative stress markers (SOD, GSH, CAT, MDA, and NO), inflammatory cytokines (IL-6, IL-1β, TNF-α), neurotrophic factors (CREB, BDNF), apoptotic markers (NFkB, caspase-3, caspase-9), and neurotransmitters (NE, DA, and GABA) in METH-induced memory-impaired rats." (PMID 41010958, 2025).
fungal infection (23 papers, 2013 to 2025). "This defect leads to recurrent catalase-positive bacterial and fungal infections as well as associated granuloma formation." (PMID 25379308, 2013). "CGD is characterized by susceptibility to catalase-positive bacterial and fungal infections." (PMID 27222657, 2016). "Taken together, these data support an increased production of catalase under established fungal infections, which decreases under prolonged exposure to bacterial coinfection." (PMID 35862772, 2022). "Collectively, photoinactivation of catalase reduces the virulence of C. albicans, thus rendering this pathogen highly susceptible to exogenous H2O2 attack in a clinically relevant mice fungal infection model." (PMID 35119220, 2022). "With these in vitro implications, we query the clinical utilization of photoinactivation of catalase against fungal infections." (PMID 35119220, 2022). "Collectively, our findings provide a novel catalase‐targeting strategy to treat multidrug resistant fungal infections." (PMID 35119220, 2022). "We found significant interactions of fungal infection and Wolbachia for expression of the catalase gene in both mosquito species (Ae." (PMID 34843477, 2021). "Our gene expression analysis of antioxidant defense genes indicate that the catalase gene is a critical component in the mosquito responses to fungal infections." (PMID 34843477, 2021). "albopictus mosquitoes presented greater expression of catalase compared to their W+ counterpart when challenged with fungal infection and that difference was significant in pairwise comparisons for B. brongniartii, but not for B. bassiana infection." (PMID 34843477, 2021). "The effects of fungal infection on catalase (CAT), SOD and GPx activities in the hemolymph of wax moth larvae were also examined." (PMID 32012188, 2020). "The activities of ROS scavenging enzymes POD, APX, and CAT were also increased by 1.3- to 1.7-fold upon fungal infection." (PMID 28769890, 2017). "In P. Americana, M. anisopliae fungal infections initiate oxidative stress in the midgut, fat body, whole body and hemolymph, and decrease the CAT activity of fat body and midgut." (PMID 27227835, 2016). "In Periplaneta Americana, M. anisopliae, Isaria fumosoroseus and Hirsutella thompsonaii fungal infections initiate oxidative stress in the midgut, fat body, whole body and hemolymph, and decrease the CAT activity of fat body and midgut." (PMID 27227835, 2016). "The expression of TLP inhibited POD, SOD, APX, and CAT activities under fungal infection." (PMID 37628673, 2023). "In response to the two bacterial pathogens, there was no significant change in POD or SOD, and the activities of APX and CAT increased and decreased, respectively, after the knockout of SlTLP5 and SlTLP6, the results of which were similar to those after fungal infection." (PMID 37628673, 2023). "Płażek and Żur indicated that low activity of CAT could be a marker of a plant resistance to a fungal infection, as CAT decomposes H2O2 that is necessary for the defense as a signal molecule." (PMID 34299055, 2021). "The rate the WT strain killed both sexes of the Actin-GAL4 > UAS-Catalase adults was nearly twofold faster than the Actin-GAL4 (P < 0.05), suggesting that insect-derived oxidative stress is an important factor that limits fungal infection." (PMID 39287372, 2024). "Herein, exogenous GABA has a notable impact on CAT and POX enzyme activities in wheat cultivars, enhancing the plant’s defense response to fungal infection." (PMID 39409662, 2024). "The fungal inoculation also enhanced the activity of ROS scavenging enzymes CAT, POD, and APX which advocated the presence of high oxidative stress during fungal infection." (PMID 28769890, 2017). "In addition, SOD, APX, CAT, and GR activities were greatest earlier in the B. maydis infection process while SOD, CAT, and GR activities were higher at the advanced stage of fungal infection." (PMID 38498536, 2024).
fungal infection (continued). "Catalase, unlike APX or POX, degrades H2O2 without requiring a reducing agent (such as ascorbate or glutathione), and its activity was enhanced by octanoic acid in triggering pre-fungal infection resistance." (PMID 39056674, 2024).